DBN1 (drebrin 1)
Description:
Actin cytoskeleton-organizing protein that plays a role in the formation of cell projections. Required for actin polymerization at immunological synapses (IS) and for the recruitment of the chemokine receptor CXCR4 to IS. Plays a role in dendritic spine morphogenesis and organization, including the localization of the dopamine receptor DRD1 to the dendritic spines (By similarity). Involved in memory-related synaptic plasticity in the hippocampus (By similarity).
Synonyms: D0S117E
Tractability: Antibody: its Gene Ontology location is reachable by antibodies, with medium confidence. PROTAC: ubiquitination databases record sites on it; its protein half-life has been measured.
Target class: Structural protein
Gene: Protein-coding gene on chromosome 5 (177,456,607 to 177,474,401, reverse strand). Ensembl gene ENSG00000113758.
Subcellular location: Cytoplasm; Cell projection, dendrite; Cytoplasm, cell cortex; Cell junction; Cell projection, growth cone
Subcellular location (Human Protein Atlas): Plasma membrane; Actin filaments
Pathways (Reactome):
Signal Transduction: RHOBTB1 GTPase cycle; RHOBTB2 GTPase cycle; RHOD GTPase cycle; RHOH GTPase cycle
Gene Ontology:
Molecular function: cadherin binding; protein binding; protein sequestering activity; actin binding; profilin binding
Biological process: actin filament organization; positive regulation of dendritic spine morphogenesis; positive regulation of receptor localization to synapse; positive regulation of synaptic plasticity; regulation of dendrite development; regulation of neuronal synaptic plasticity
Cellular component: actin cytoskeleton; anchoring junction; cytoplasm; cytoskeleton; dendrite; actomyosin; cortical cytoskeleton; growth cone; cell cortex; cell periphery; neuron projection
Genetic constraint (gnomAD): Loss-of-function variants: 16 observed, 70.01 expected, observed/expected ratio (o/e) 0.23, 90% interval 0.15 to 0.35. The upper end of that interval is the gene's LOEUF score, 0.35, which puts it in group 1 of 6, group 1 being the genes least tolerant of losing a copy. Missense variants: 827 observed, 846.27 expected, observed/expected ratio (o/e) 0.98, 90% interval 0.92 to 1.03. Synonymous variants: 368 observed, 353.11 expected, observed/expected ratio (o/e) 1.04, 90% interval 0.96 to 1.14.
Homologues: Orthologues: chimpanzee DBN1 (99% identical), macaque DBN1 (99% identical), dog DBN1 (90% identical), mouse Dbn1 (90% identical), rat Dbn1 (90% identical), pig DBN1 (88% identical), guinea pig DBN1 (86% identical), rabbit DBN1 (60% identical), tropical clawed frog dbn1 (49% identical), zebrafish dbn1 (43% identical). Paralogues in human: DBNL (19% identical), HCLS1 (11% identical), CTTN (11% identical), COTL1 (4% identical).